TMEM205 (transmembrane protein 205)
Description:
In cancer cells, plays a role in resistance to the chemotherapeutic agent cisplatin.
Synonyms: UNQ501; MBC3205
Tractability: Antibody: UniProt predicts a signal peptide or a membrane-spanning region. PROTAC: ubiquitination databases record sites on it; its protein half-life has been measured.
Gene: Protein-coding gene on chromosome 19 (11,342,776 to 11,346,518, reverse strand). Ensembl gene ENSG00000105518.
Subcellular location: Membrane
Subcellular location (Human Protein Atlas): Endoplasmic reticulum; Nuclear membrane; Nucleoplasm
Gene Ontology:
Molecular function: protein binding
Cellular component: membrane
Genetic constraint (gnomAD): Loss-of-function variants: 12 observed, 23.25 expected, observed/expected ratio (o/e) 0.52, 90% interval 0.33 to 0.84. The upper end of that interval is the gene's LOEUF score, 0.84, which puts it in group 3 of 6, group 1 being the genes least tolerant of losing a copy. Missense variants: 236 observed, 253.07 expected, observed/expected ratio (o/e) 0.93, 90% interval 0.84 to 1.04. Synonymous variants: 86 observed, 103.73 expected, observed/expected ratio (o/e) 0.83, 90% interval 0.69 to 0.99.
Homologues: Orthologues: chimpanzee TMEM205 (100% identical), macaque TMEM205 (98% identical), pig TMEM205 (88% identical), rat Tmem205 (83% identical), guinea pig TMEM205 (79% identical), mouse Tmem205 (79% identical), rabbit TMEM205 (77% identical), zebrafish tmem205 (43% identical), Caenorhabditis elegans lea-1 (24% identical).
Diseases named in the same sentence as TMEM205 in open-access papers:
TMEM205 is named in the same sentence as 15 diseases in open-access papers, as found by Europe PMC text mining. Sharing a sentence is not in itself a finding about the gene and the disease. The quoted sentences say what the papers report.
ovarian carcinoma (5 papers, 2024 to 2025). A malignant neoplasm originating from the surface ovarian epithelium. "Although research on this gene is currently limited, evidence suggests that mutations in TMEM205 may be associated with chemotherapy resistance in ovarian cancer." (PMID 40678495, 2025). "Through its regulation of Rab11 expression, TMEM205 facilitates the development of platinum-resistant ovarian cancer by promoting exosome secretion." (PMID 40757000, 2025). "Recent research has focused on developing nitroxide tethering diarylpiperidone compounds that target TMEM205, demonstrating their ability to reduce exosome secretion and inhibit platinum efflux in platinum-resistant ovarian cancer." (PMID 40757000, 2025). "Recent study has revealed that STAT3 or TMEM205 co-localizes with EV secretion proteins, specifically Rab8 or Rab11, and its expression is upregulated in ovarian cancer cells, where it plays a crucial role in regulating EV secretion." (PMID 39414985, 2024). "TMEM205, a transmembrane glycoprotein, is particularly noteworthy due to its diverse functions and interactions with various proteins which have implications for different cancer types, including ovarian cancer." (PMID 40210758, 2025). "Out of larger subset of candidate biomarker proteins our studies identified, TMEM205 and CFH were found to have the most prominent and consistently increased expression in platinum-resistant ovarian cancer." (PMID 40210758, 2025). "Related studies have found that TMEM205 overexpressed in DDP-resistant ovarian cancer and participated in the therapeutic process of DDP for ovarian cancer." (PMID 38850316, 2024).
lung carcinoma (3 papers, 2014 to 2023). "The main polymorphisms on transporters OCT2, LRP, AQP2, AQP9 and TMEM205 genes were genotyped in 338 lung cancer patients." (PMID 24643204, 2014). "This study showed that TMEM205 rs896412 might be significantly associated with chemotherapy response in all lung cancer patients (genotypic and recessive models), male subgroup (genotypic and recessive models) and subgroup of age >55 (genotypic model)." (PMID 24643204, 2014). "In conclusion, the genetic polymorphisms in OCT2, AQP2, AQP9 and TMEM205 may contribute to chemotherapy response in lung cancer patients." (PMID 24643204, 2014). "The expression of TMEM48 and TMEM97 are potential prognostic biomarkers for lung cancer, while TMEM45A and TMEM205 are implicated in tumor growth and invasion." (PMID 38248651, 2023). "A growing number of studies revealed that TMEMs were differentially expressed among human cancers, including TMEM116 and TMEM229A in lung cancer, TMEM205 in hepatocellular carcinoma, TMEM168 in glioblastoma, and TMEM180 in colorectal cancer." (PMID 36313638, 2022). "We thought that TMEM205 may play an important role in lung cancer platinum-based chemotherapy response and would also be a possible biomarker for lung cancer chemotherapy." (PMID 24643204, 2014). "Our results showed that SNPs rs195854 (OCT2) and rs186941 (OCT2), rs7314734 (AQP2), rs1516400 (AQP9), and rs896412 (TMEM205) might be related with chemotherapy response in lung cancer patients." (PMID 24643204, 2014).
epidermoid carcinoma (2 papers, 2022 to 2024). "Published data to this point suggests that TMEM205 is a hypothetical membrane protein which may be involved in chemoresistance in epidermoid carcinoma and that Rab8 enhances this chemoresistance." (PMID 36476493, 2022).
gastric cancer (2 papers, 2024 to 2025). A primary or metastatic malignant neoplasm involving the stomach. "Our results showed that TMEM205 reduced the sensitivity of gastric cancer cells to cisplatin, which was closely associated with cisplatin resistance in gastric cancer cells, and silencing TMEM205 reversed cisplatin resistance in gastric cancer cells." (PMID 38850316, 2024). "To further investigate the effect of TMEM205 on gastric cancer progression, we injected si-TMEM205-2-treated or untreated SGC-7901/DDP cells into thymus-free nude mice, respectively, and established a xenograft tumor model." (PMID 38850316, 2024). "The results showed that the combined effect of si-TMEM205-2 or DDP significantly inhibited the growth of gastric cancer tumors compared to si-TMEM205-2 or DDP alone." (PMID 38850316, 2024). "Moreover, TMEM205-induced polarization of M2-TAMs further accelerates gastric cancer progression." (PMID 40977700, 2025).
hepatocellular carcinoma (2 papers, 2020 to 2022). A malignant tumor that arises from hepatocytes. "RNA-seq and clinical data from hepatocellular carcinoma patients in the International Cancer Genome Consortium (ICGC) also showed significant differential expression of TMEM205 (P < 0.001) and association between low TMEM205 expression and poor survival (P < 0.001)." (PMID 33193690, 2020).
Obesity (1 paper, 2024). Accumulation of substantial excess body fat. "Our study presents compelling evidence that highlights the critical role of obesity-associated EV carrying oncogenic proteins, including TMEM205, STAT5, and FAS in the pathogenesis of EC." (PMID 39414985, 2024). "While the oncogenic roles of STAT5, FAS, and TMEM205 have been investigated in various cancers, their involvement in the regulation of EV secretion and obesity-associated EC remains incompletely understood." (PMID 39414985, 2024). "Our current study has identified the regulation of EV secretion and the expression of oncogenic proteins, specifically TMEM205, STAT5, and FAS, in obesity-associated EC tissues and serum." (PMID 39414985, 2024). "Furthermore, our investigation uncovered distinct protein expression patterns in obesity-related EC which includes elevated levels of oncogenic proteins such as TMEM205, STAT5, FAS and identified downregulation of tumor suppressor protein PIAS3." (PMID 39414985, 2024). "This unique feature imparts antioxidant protection to noncancerous tissues, making DAP compounds a potentially safe inhibitor for EV regulating oncogenic proteins (STAT3, FAS, and TMEM205), with applications in preventing obesity-mediated EC and other cancers within an obese microenvironment." (PMID 39414985, 2024).
steatosis (1 paper, 2025). Increased lipid within the cytoplasm of cells. "In macrophages, the STING–YAP axis regulates steatosis by reprogramming lipid metabolism through a pathway involving transmembrane protein 205 (TMEM205), mitofusin 2 (MFN2), and protein disulfide isomerase (PDI)." (PMID 40392981, 2025).
tumor (7 papers, 2018 to 2025). "A correlation analysis was conducted, and TMEM205 expression in tumor tissues was found to be significantly associated with the proportion of macrophages (Pearson r = 0.45, p < 0.0001)." (PMID 33193690, 2020). "TMEMs, such as TMEM45A and TMEM205, have also been implicated in tumor progression and invasion but also in chemoresistance." (PMID 30574087, 2018). "In addition, TMEM205 promotes GC progression by inducing M2 polarization of tumor-associated macrophages (TAMs)." (PMID 38850316, 2024). "In the current study, we not only found significant difference in TMEM205 expression between normal tissue and tumor tissue (p < 0.001) but also demonstrated that low TMEM205 expression was independently associated with poor OS (p = 0.032) and DSS (p = 0.002) in HCC patients from the TCGA cohort." (PMID 33193690, 2020). "Additionally, TMEM205 expression in tumor tissues was significantly associated with the proportion of macrophages (Pearson r = 0.45, p < 0.0001)." (PMID 33193690, 2020). "Research on TMEM205 is still in its infancy, and our study provides strong evidence that TMEM205 plays an important role in tumor progression and reversal of drug resistance." (PMID 38850316, 2024). "In the future, we will launch a series of studies around TMEM205 to unveil the various roles it plays in the tumor microenvironment." (PMID 38850316, 2024). "Members of this family can act as both oncogenes, such as TMEM45A and TMEM205, or tumor suppressors, such as TMEM25 and TMEM7." (PMID 36077735, 2022). "For pathological examination of specimens, all tumor or control samples (ovary and fallopian tube) were probed with anti-TMEM205 for all the treatment groups." (PMID 36476493, 2022). "We also found a positive correlation between TMEM205 expression and the proportion of macrophages in tumor tissues (Pearson r = 0.45, p < 0.0001)." (PMID 33193690, 2020). "Through t-test with the TCGA RNA-seq datasets, we found differential expression of TMEM205 in 50 paired tumor and normal tissues (p < 0.001)." (PMID 33193690, 2020). "Using Kaplan–Meier analysis and univariate Cox regression analysis with the TCGA RNA-seq datasets, low TMEM205 expression in tumor tissues was found to predict poor disease-specific survival (DSS; p = 0.005) in HCC patients." (PMID 33193690, 2020). "We validated the significant difference of TMEM205 expression between normal tissues and tumor tissues in the ICGC cohort (p < 0.001)." (PMID 33193690, 2020). "In this study, we analyzed the RNA-seq and clinical data of 371 patients from The Cancer Genome Atlas (TCGA) and found significant differential expression of TMEM205 between normal and tumor tissues (P < 0.001)." (PMID 33193690, 2020). "Transmembrane protein 205 (TMEM205) is one of several transmembrane proteins linked to PDAC prognosis and is involved in membrane trafficking, signaling, and tumor microenvironment modulation highlighting their potential as both diagnostic and therapeutic targets." (PMID 41007761, 2025). "Finally, we found that TMEM205 expression appeared to inhibit IL-10 expression (Pearson r = −0.22, p < 0.0001), while TMEM205 expression was positively correlated with the proportion of CD8+ T cells in tumor tissues (Pearson r = 0.26, p < 0.0001)." (PMID 33193690, 2020). "In recent years, more and more studies have pointed out the associations between certain transmembrane (TMEM) family proteins and tumor progression, but the role of TMEM205 remains unclear." (PMID 33193690, 2020). "Previous studies have reported associations between many members of the TMEM family and tumor progression, but the role of TMEM205 was not previously established." (PMID 33193690, 2020). "In conclusion, TMEM205 might improve HCC patients’ prognosis by reducing the levels of immunosuppressive cells (M2 macrophages and Tregs) and facilitating the infiltration of cytotoxic T cells into the tumor microenvironment." (PMID 33193690, 2020).
tumor (continued). "Thus, there might also be a negative correlation between TMEM205 expression and the proportion of M2 macrophages in tumor tissues." (PMID 33193690, 2020).
cancer (4 papers, 2022 to 2025). A tumor composed of atypical neoplastic, often pleomorphic cells that invade other tissues. "However, whether TMEM205 could affect cancer progression by regulating the Wnt/β-catenin pathway had not reported." (PMID 38850316, 2024). "However, whether TMEM205 involved in cancer metastasis had no studies." (PMID 38850316, 2024). "Our exploration revealed a significant increase in EV secretion carrying oncogenic proteins (TMEM205, STAT5, and FAS) in adipose and uterine tissues/serum samples from obese EC patients compared to control (without cancer)." (PMID 39414985, 2024).
cardiovascular diseases (1 paper, 2022). "In the dilated stage, TMEM205, ADIRF, C6H4orf48, NGRN, PROSER1, ERICH2, and CINP were not previously linked to cardiovascular diseases." (PMID 35625658, 2022).
infection (1 paper, 2022). The state of being infected such as from the introduction of a foreign agent such as serum, vaccine, antigenic substance or organism. "TMEM205 interacts with glycoprotein-C of oHSV post-infection; both of these proteins undergo ubiquitination and ultimately get shuttled outside the cell via exosomes." (PMID 36476493, 2022).
TMEM205 also shares sentences with these, for which no sentence is quoted: bacterial infections (1 paper); colorectal cancer (1); glioblastoma (1); ovarian clear cell cancer (1).